PDE4D (phosphodiesterase 4D)
Description:
Hydrolyzes the second messenger cAMP, which is a key regulator of many important physiological processes.
Synonyms: DPDE3; ACRDYS2; HSPDE4D; PDE43; PDE4DN2; STRK1
Tractability: Small molecule: an approved drug acts on it; a structure with a bound ligand is known; a high-quality ligand is known; it has a high-quality binding pocket; it belongs to a druggable protein family. Antibody: UniProt places it where antibodies can reach, with high confidence; its Gene Ontology location is reachable by antibodies, with high confidence. PROTAC: it is named in the literature on targeted protein degradation; UniProt records ubiquitination sites on it; ubiquitination databases record sites on it; its protein half-life has been measured; a small molecule that binds it is known.
Target class: Phosphodiesterase 4D; Phosphodiesterase 4; Phosphodiesterase; Enzyme
Chemical probes: PD004582 (high quality), PD082823, roflupram
Safety:
Unwanted effects reported when the protein is acted on. In parentheses: how it was acted on, where the effect was seen, and who reports it.
anti-inflammatory activities (inhibition; immune, central nervous system; source: Bowes et al. (2012))
antidepressant-like activities (inhibition; immune, central nervous system; source: Bowes et al. (2012))
arteritis (inhibition; immune, central nervous system; source: Bowes et al. (2012))
emesis (inhibition; immune, central nervous system; source: Bowes et al. (2012))
possible thymus atrophy (inhibition; immune, central nervous system; source: Bowes et al. (2012))
vasculitis (inhibition; immune, central nervous system; source: Bowes et al. (2012))
Gene: Protein-coding gene on chromosome 5 (58,969,038 to 60,522,120, reverse strand). Ensembl gene ENSG00000113448.
Subcellular location: Apical cell membrane; Cytoplasm; Membrane; Cytoplasm, cytoskeleton; Cytoplasm, cytoskeleton, microtubule organizing center, centrosome
Subcellular location (Human Protein Atlas): Cytosol; Plasma membrane; Nuclear membrane; Nucleoplasm; Primary cilium
Pathways (Reactome):
Signal Transduction: DARPP-32 events; G alpha (s) signalling events
Cellular responses to stimuli: Turbulent (oscillatory, disturbed) flow shear stress activates signaling by PIEZO1 and integrins in endothelial cells
Gene Ontology:
Molecular function: 3',5'-cyclic-AMP phosphodiesterase activity; ATPase binding; cAMP binding; heterocyclic compound binding; protein binding; scaffold protein binding; transmembrane transporter binding; 3',5'-cyclic-GMP phosphodiesterase activity; 3',5'-cyclic-nucleotide phosphodiesterase activity; beta-2 adrenergic receptor binding; calcium channel regulator activity; enzyme binding; signaling receptor regulator activity; phosphoric diester hydrolase activity
Biological process: negative regulation of adenylate cyclase-activating G protein-coupled receptor signaling pathway; positive regulation of interleukin-2 production; positive regulation of interleukin-5 production; positive regulation of type II interferon production; regulation of cell communication by electrical coupling involved in cardiac conduction; T cell receptor signaling pathway; adrenergic receptor signaling pathway; establishment of endothelial barrier; negative regulation of cAMP/PKA signal transduction; negative regulation of heart contraction; negative regulation of relaxation of cardiac muscle; positive regulation of heart rate; regulation of calcium ion transmembrane transport via high voltage-gated calcium channel; regulation of cardiac muscle cell contraction; regulation of heart rate; regulation of release of sequestered calcium ion into cytosol by sarcoplasmic reticulum; cAMP catabolic process; signal transduction
Cellular component: calcium channel complex; plasma membrane; cytosol; voltage-gated calcium channel complex; apical plasma membrane; centrosome; cytoplasm; cytoskeleton; membrane
Genetic constraint (gnomAD): Loss-of-function variants: 14 observed, 54.24 expected, observed/expected ratio (o/e) 0.26, 90% interval 0.17 to 0.4. The upper end of that interval is the gene's LOEUF score, 0.4, which puts it in group 1 of 6, group 1 being the genes least tolerant of losing a copy. Missense variants: 531 observed, 701.1 expected, observed/expected ratio (o/e) 0.76, 90% interval 0.7 to 0.81. Synonymous variants: 270 observed, 261.64 expected, observed/expected ratio (o/e) 1.03, 90% interval 0.93 to 1.14.
Homologues: Orthologues: chimpanzee PDE4D (99% identical), macaque PDE4D (99% identical), dog PDE4D (99% identical), rabbit PDE4D (98% identical), pig PDE4D (98% identical), mouse Pde4d (97% identical), rat Pde4d (97% identical), guinea pig PDE4D (95% identical), tropical clawed frog pde4d (86% identical), zebrafish pde4d (73% identical), Drosophila melanogaster Pde8 (17% identical), Caenorhabditis elegans pde-3 (16% identical), and 2 more. Paralogues in human: PDE4B (64% identical), PDE4A (63% identical), PDE4C (58% identical), PDE1C (20% identical), PDE3A (19% identical), PDE1B (19% identical), PDE8B (19% identical), PDE3B (19% identical), PDE8A (19% identical), PDE11A (18% identical), PDE1A (18% identical), PDE6A (18% identical), and 8 more.
Diseases named in the same sentence as PDE4D in open-access papers:
PDE4D is named in the same sentence as 179 diseases in open-access papers, as found by Europe PMC text mining. Sharing a sentence is not in itself a finding about the gene and the disease. The quoted sentences say what the papers report.
Stroke (26 papers, 2005 to 2025). Sudden impairment of blood flow to a part of the brain due to occlusion or rupture of an artery to the brain. "This study provides a better understanding of the association of PDE4D SNP rs2910829 with stroke susceptibility in Chinese individuals." (PMID 38465333, 2024). "This meta-analysis reveals significant relationships between the PDE4D SNP rs2910829 and susceptibility to stroke and subtype-LAA stroke in Chinese individuals, and further investigations are warranted to evaluate this effect." (PMID 38465333, 2024). "An Icelandic study identified a significant correlation of the phosphodiesterase 4D (PDE4D) single-nucleotide polymorphism (SNP) rs2910829 with stroke susceptibility." (PMID 38465333, 2024). "The deCODE group observed the association of PDE4D variants with stroke, especially with CE and LAA stroke." (PMID 38465333, 2024). "A decade of additional studies summarized by meta-analysis confirmed that some PDE4D variants are indeed related to stroke." (PMID 38502340, 2024). "PDE4D is associated with inflammation and reduced PDE4D is thought to increase the risk of atrial fibrillation, which in turn increases stroke risk." (PMID 36973604, 2023). "As shown in the Icelandic study, SNP in the PDE4D gene thought to be associated with stroke had subtle effects on PDE4D expression and even on the expression of transcripts encoding different PDE4D isoforms." (PMID 30800055, 2019). "PDE4D gene encodes a phosphodiesterase enzyme that regulates cAMP levels in the body and was first identified as a candidate gene for stroke by the DeCODE study." (PMID 23505425, 2013). "We observed a doubling in the odds (OR 2.20; 95% CI, 1.21–3.99) or a ∼120% increase in the risk of developing stroke per copy of the risk allele of PDE4D SNP 83 for overall ischemic stroke." (PMID 23505425, 2013). "Among the literature investigating the associations between the PDE4D gene and stroke, only one study included IMT and plaque as phenotypes of interest." (PMID 20540798, 2010). "Rs702553 at the PDE4D gene was selected because it conferred a risk for young stroke in our previous report." (PMID 20540798, 2010). "Mutations of PDE4D have been associated with stroke risk in several populations, possibly related to the role of PDE4 in modulating inflammatory processes, although the causal nature of the association remains controversial." (PMID 17903308, 2007). "Assuming a contribution of PDE4D to the risk of osteoporosis as well as stroke, it is possible that different domains are involved in the different diseases." (PMID 15752431, 2005). "This meta-analysis suggests that SNP rs2910829 in PDE4D may contribute to stroke susceptibility, especially LAA stroke susceptibility, in Chinese individuals." (PMID 38465333, 2024). "Among 260 PDE4D gene SNPs, six were found to be significantly associated with stroke." (PMID 35326259, 2022). "Genetic association of PDE4D with stroke was shown previously in an Icelandic GWAS study." (PMID 30800055, 2019). "In this study, we found that the TT genotype of SNP87 in PDE4D was associated with an increased risk for 3-month unfavorable outcome after total ischemic stroke, as well as stroke due to large-artery atherosclerosis and small-artery occlusion, in a Chinese population." (PMID 28225001, 2017). "Polymorphisms within PDE4D have been associated with stroke, and bone mineral density." (PMID 21625484, 2011). "The phosphodiesterase 4D (PDE4D) gene was reported as a susceptibility gene to stroke." (PMID 20540798, 2010). "The phosphodiesterase 4D (PDE4D) gene was identified as a stroke susceptibility." (PMID 20540798, 2010). "Interestingly, four of these genes (KCNMB1, NEDD4L, ADD1 and NPR3) have been implied in genetic susceptibility for hypertension, while two genes have been associated with genetic susceptibility for stroke (PDE4D) or myocardial infarction (ADD1)." (PMID 19750006, 2009).
Stroke (continued). "Benzoin, a TCM used for stroke treatment, exerts its effects through targets such as phosphodiesterase 4D (PDE4D), ACE, and transthyretin (TTR), as suggested by network pharmacology and molecular docking studies." (PMID 40606624, 2025). "Phosphodiesterase 4D (PDE4D) is a protein encoded by the PDE4D gene and has been associated with multiple diseases, including asthma, COPD, stroke and bone mineral density." (PMID 38730525, 2024). "Regarding stroke cases, polymorphisms in some genes such as MTHFR, eNOS, ACE, AGT, ApoE, PON1, PDE4D were associated with a higher risk of ischemic stroke." (PMID 38478535, 2024). "The deCODE Genetics group revealed the association of PDE4D variants with IS risk, particularly strong with the risk of cardioembolic (CE) and large artery atherosclerosis (LAA) stroke." (PMID 38172709, 2024). "Another study identified a strong association between the phosphodiesterase 4D gene (PDE4D; OMIM 600129*) and two major subtypes of stroke, cardiogenic and carotid stroke." (PMID 35326259, 2022). "Among 260 phosphodiesterase 4D (PDE4D) single-nucleotide polymorphisms (SNPs) examined, six were significantly associated with stroke after adjustment for multiple comparisons." (PMID 24090469, 2013). "The results from carotid atherosclerotic phenotypes were in concordance with the results observed in our previous PDE4D young stroke study where the TT genotype was over-represented in young stroke cases than in the controls (23.9% vs. 15.9%, p = 0.01)." (PMID 20540798, 2010). "We selected rs702553 at the PDE4D gene as the candidate locus based on our previous findings in the young stroke study." (PMID 20540798, 2010). "Our results indicate that the influence of the PDE4D gene begins long before the ischemic infarct, and its genetic effect on stroke is at least partially attributed to the wall thickening and plaque formation in the carotid arteries." (PMID 20540798, 2010). "As stated in the introduction, PDE4D may be implicated in the pathogenesis of stroke, particularly the pathogenesis of LAA and CE stroke." (PMID 38465333, 2024). "PDE4D is related to a variety of neurological diseases, such as AD, stroke, and epilepsy." (PMID 32849849, 2020). "Last, the characteristic influences of the PDE4D influences on the topologies of functional brain networks in patients with other brain neural disorder diseases (e.g., epilepsy, stroke) remain largely unknown." (PMID 32849849, 2020). "Recently, PDE4D has been shown to play an important role in vascular diseases, including stroke." (PMID 25120928, 2014). "Therefore, PDE4D may be involved in the pathogenesis of stroke, particularly the pathogenesis of LAA and CE stroke." (PMID 38465333, 2024). "Fine mapping of the locus revealed that phosphodiesterase 4D (PDE4D, OMIM: 600129) may be a susceptibility gene, and subsequent association analysis in an Icelandic stroke cohort identified several significant single-nucleotide polymorphisms (SNPs) and haplotypes in PDE4D." (PMID 38465333, 2024). "Despite recent studies in the Han Chinese and Korean showed significant associations between the PDE4D gene and certain stroke subtypes, the largest PDE4D association study conducted in the Asian population (including 2847 stroke cases and 4464 controls in Japan) showed a negative result." (PMID 20540798, 2010). "Of these, four (PDE4D, PDE3A, PDE3B, PDE6B) were ranked in the top 1% by the exome method for stroke." (PMID 37492104, 2023). "The present study demonstrates a sex-differential effect of PDE4D on IMT, plaque index and stroke, which highlights its influence on various aspects of atherogenesis." (PMID 20540798, 2010). "Two widely investigated genes, phosphodiesterase 4 D (PDE4D) and lipoxygenase-activating protein (ALOX5AP), have never been confirmed in meta-analyses of stroke." (PMID 23356535, 2013).
prostate carcinoma (25 papers, 2014 to 2025). A carcinoma that arises from epithelial cells of the prostate gland. "CDH4 and PDE4D can be used as early diagnostic markers of gastrointestinal tumor and prostate cancer, respectively." (PMID 34323415, 2021). "The risk, of either developing metastases or dying from prostate cancer (6 and 5 out of the 31 patients, respectively), increases strongly with reduced expression levels of multiple prostate-expressed long PDE4D isoforms." (PMID 31275657, 2019). "The AUC of the base model of the CAPRA score alone was increased by 10%, from 0.77 to 0.87, when combined with all three prostate cancer relevant long PDE4D transcripts into a single risk prediction algorithm." (PMID 31275657, 2019). "We recently described the association of the expression of the prostate cancer biomarker PDE4D7 to postsurgical biochemical relapse based on the quantitation of the PDE4D transcript in surgical resection tissues." (PMID 30147955, 2018). "The downregulation of PDE4D expression was found recently to increase the proliferation of prostate cancer cells and associated with the progression of prostate cancer." (PMID 30482227, 2018). "PDE4D has also been implicated in other cancers, such as prostate cancer, medulloblastoma, and leukemia, indicating that PDE4D may be a more general target for cancer therapy." (PMID 39202484, 2024). "PDE4D was demonstrated to be a tumor-promoting factor in prostate cancer and BRAF-mutated melanoma." (PMID 36816023, 2023). "Additionally, they found that reduced expression of multiple long PDE4D isoforms increased the risk of developing metastases or dying from prostate cancer." (PMID 37830741, 2023). "We have previously published that the clinical-genomic risk score CAPRA&PDE4D5/7/9, which is a combination model of the CAPRA score with the expression levels of the respective PDE4D transcripts, is associated with prostate cancer progression after surgical removal of the prostate." (PMID 36612262, 2022). "Since, partial or complete deletions of one or both alleles of the PDE4D gene have been reported previously in prostate cancer we utilized TCGA SNP array data of matching patient samples to assess the potential impact of deletions occurring in PDE4D on isoform expression." (PMID 27683107, 2016). "Recent studies have implicated individual PDE4D transcripts in the development of prostate cancer." (PMID 26575822, 2015). "The differential roles of PDE4D and PDE4D7 in prostate cancer indicate the complex involvement of PDE4D subtypes in the development of prostate cancer, highlighting the need for further research to elucidate the specific functions of each subtype." (PMID 40129976, 2025). "The down-regulated PDE4D was reported recently to promote the progression of prostate cancer and bladder cancer." (PMID 38514754, 2024). "mRNA levels of PDE4 families and specific isoforms were analysed in 19 prostate cancer cell lines and xenografts and total PDE4D mRNA was found to decrease during the transition to androgen-insensitivity." (PMID 37830741, 2023). "Next, the expression of other PDE4D isoforms in prostate cancer was investigated due to their ability to regulate downstream signalling pathways." (PMID 37830741, 2023). "PDE4D isoforms are also down-regulated in androgen-insensitive prostate cancer cell lines, with PDE4D7 being of particular importance in regulating prostate cancer proliferation and suggested as a novel tumour biomarker." (PMID 37830741, 2023). "In human CRPC prostate cancer, PDE4D is highly overexpressed and inhibition of PDE4D reduces the growth of both prostate cancer cells in vitro and in vivo." (PMID 34066000, 2021). "In summary, inhibition of PDE4D by Eggmanone or siRNA knockdown rapidly reduces the proliferation of chemo-resistant prostate cancer cells." (PMID 34066000, 2021).